TLR4 (toll like receptor 4)
Diseases named in the same sentence as TLR4 in open-access papers (continued):
Sharing a sentence is not in itself a finding about the gene and the disease.
infection (continued). "During infection, hepcidin is directly induced by LPS via TLR4 activation and during inflammation hepcidin is induced by IL-6." (PMID 25762501, 2014). "One similarity with our data is that mice treated with TLR4 antagonist, Eritoran, or TLR4−/− mice had reduced lung pathology to infection with influenza virus, which is characterized by the reduction of viral burden and proinflammatory cytokine expression." (PMID 25188232, 2014). "We also observed that FIP200 siRNA silencing in MH-S cells significantly decreased protein expression of HMGB1, RAGE and TLR4 following infection by western blotting." (PMID 24923305, 2014). "In the beginning of infection, live mycobacteria, induced higher induction of p38 and pGSK3αβ than the virulence factor 19 kDa and the TLR4 agonist LPS." (PMID 24489729, 2014). "At the early phase of infection, analysis of the spleen provides an insight into how TLR3 and TLR4 molecules modulate innate immune and inflammatory responses immediately after infection, because JEV was administered intraperitoneally." (PMID 25188232, 2014). "Despite heavy colonization, Tlr4−/−/Sigirr−/− mice were largely unresponsive to infection by C. jejuni, whereas Tlr2−/−/Sigirr−/− mice developed exaggerated inflammation and pathology." (PMID 25033044, 2014). "Loss of TLR4 activity in HeJ mice may contribute to multiple sequential deficiencies in immune activity including decreased production of antimicrobial defenses by epithelia, delayed recruitment of innate immune leukocytes to the site of infection or compromised activation of adaptive immunity." (PMID 24497924, 2014). "Antibody blocking of TLR2 or TLR4 before infection decreased epithelial IL-6 secretion (p = 0.0011 and p = 0.0047 respectively)." (PMID 24489729, 2014). "Corneas from each group were dissected at the indicated time after infection and the expression of TLR4 and CXCL2 were analyzed by RT-PCR." (PMID 24633052, 2014). "Y. pestis expresses a tetra-acylated lipid A that functions as a TLR4 antagonist at 37°C, which allows this pathogen to remain undetected in the bloodstream during early stages of infection." (PMID 25010102, 2014). "Soluble forms of TLR2 and TLR4 dampen the host immune response against infection by preventing the activation of TLR-mediated signaling." (PMID 24695582, 2014). "Fip200 deficiency significantly reduced the expressions of HMGB1, RAGE and TLR4 in lung tissue after PAO1 infection." (PMID 24923305, 2014). "Uniquely, P. gingivalis evasion of host innate immunity at TLR4 results in progression of inflammation at a site that is distant from local infection by gaining access to the vasculature." (PMID 25010102, 2014). "While TLR4 plays a protective role in infections with L. major, it appears to have an anti-inflammatory effect in macrophages infected with L. mexicana, a species closely related to the L. amazonensis used in our study." (PMID 24497831, 2014). "To further pinpoint the underlying cellular mechanism of these microbial effects on TLR2 and TLR4 expression we used a sterile infection cell culture model." (PMID 25396415, 2014). "Blocking of TLR4 prior to infection increased IL-10 secretion compared to unblocked infection (p = 0.0399)." (PMID 24489729, 2014). "In contrast, the involvement of TLR2 and TLR4 in the infection by Δisp2/isp3 was further supported by colocalization." (PMID 24732131, 2014). "In this study, we observed significant increases in cellular levels of TLR4 in the colonic crypts of CR infected mice suggesting critical role(s) for TLR4 in transducing signals in response to CR infection." (PMID 24278135, 2013). "Upon infecting these mice along with WT and Sigirr −/− mice, and Tlr2 −/− and Tlr4 −/− mice, all mouse strains were found to survive the infection." (PMID 23950714, 2013). "Infection activates TLR4 signaling in host epithelial cells through direct parasite-host cell interactions." (PMID 23592986, 2013).
infection (continued). "The levels of TLR3 and TLR7-8 peaked at 5 days after infection, while the levels of TLR4 peaked at 9 days after infection." (PMID 24039959, 2013). "Previous studies demonstrated that several intracellular signaling pathways are activated in host epithelial cells following infection, including the TLR4/IKK/NF-κB and PI-3K pathways." (PMID 23592986, 2013). "Collectively, our data suggest that infections of mice with E. papillata not only induce pathogenesis in the jejunum, the final target site of E. papillata, but also induced an upregulation of TLR4 and a downregulation of MUC2." (PMID 24367242, 2013). "Even more impressive, anti-TLR4 therapy initiated as much as 13 h after the onset of infection in a model of E. coli peritoneal infection improved survival from 30 to 75%." (PMID 24302927, 2013). "Infection of H.pylori induces TLR4 expression in gastric epithelial cells, thus activates NF-κB and results in the production of various cytokines." (PMID 23437218, 2013). "Although we cannot define the exact mechanisms responsible for hMPV-induced disease in the mouse model of infection, the blunted inflammatory response could be part of the reason for the observed reduced clinical disease, both in terms of body weight loss and airway function in TLR4−/− mice." (PMID 24205331, 2013). "Infection of Tlr4−/− mice with CR elicited a much more profound response both in terms of gross morphology and crypt epithelial cell proliferation." (PMID 24278135, 2013). "HMPV replicated efficiently in the lungs of WT and TLR4−/− mice, with a peak of viral titer at day 4 p.i., and declined to undetectable levels by day 7 p.i. after infection." (PMID 24205331, 2013). "Next, we examined the contribution of β-catenin towards crypt hyperplasia in response to CR infection in the wild type and Tlr4−/− mice, respectively." (PMID 24278135, 2013). "TLR4 signaling drives IEC proliferation during infection, while TLR2 signaling promotes IEC integrity." (PMID 23950714, 2013). "We found a significant increase of TLR4 protein in cells with H.pylori infection compared with non-infection." (PMID 23437218, 2013). "Taken together, our results from the in vitro infection model reveal for the first time that there exists the pathway via TLR4-Mal/MyD88-IRAK1-NF-kB axis in human cervical epithelial cells in response to HSV-2 infection." (PMID 24278275, 2013). "Their work indicated for the first time the critical role of TLR4 in mediating innate response during primary infection and lytic replication of the latent DNA virus." (PMID 24278275, 2013). "Later on, it was observed that elastase produced by neutrophils plays a key role in the control of the infection, since this molecule activates the microbicidal mechanisms of the L. major-infected macrophages in a TLR-4-dependent manner." (PMID 24086787, 2013). "So far, we have seen that both increases in NF-κB and β-catenin signaling following CR infection coincide with colonic crypt hyperplasia in wild type as well as Tlr4−/− mice, respectively." (PMID 24278135, 2013). "We observe a moderate dependence on TRIF and IFNAR signaling when macrophages are primed with LPS prior to infection, consistent with LPS-dependent upregulation of caspase-11 expression through the TLR4-TRIF-IFNAR axis." (PMID 23762026, 2013). "In contrast, a higher infection burden was detected in cells stably expressing the TLR4-defective dominant negative (DN) mutant at 24 h and 48 h after the initial exposure to the same amount of sporozoites." (PMID 22615562, 2012). "In stark contrast, TLR4−/− mice remained largely asymptomatic up to 14 dpi, which probably resulted from the clearance of infection through reduced but adequate innate and adaptive responses." (PMID 22724018, 2012). "In vitro infection of human cervical epithelium with HSV-2 resulted in increased levels of TLR4 and TLR9 mRNA and a concomitant increase in protein expression for each TLR." (PMID 23061052, 2012).
infection (continued). "It is worth to note that in our present study both F4ab and F4ac infections down-regulated the TLR4 mRNA expression." (PMID 22823589, 2012). "The authors observed upregulation of TLR2 and TLR4 from day 1 to day 28 postinfection, and increased expression correlated with higher mRNA levels for TNFα, IL-17, IL-10, and TGFβ during early infection." (PMID 22523644, 2012). "Expression levels of TLR4 tended to be increased in infected males compared to female lymphocytes at both day 3 and 6 post infection." (PMID 23241283, 2012). "Upon infection with SE, both TLR4 and TLR21, as well as TLR15 were significantly up-regulated when compared to heterophils from line B chickens." (PMID 22783275, 2012). "HMGB1 serves as an endogenous ligand of both TLR2 and TLR4, and mediates the response to infection, injury and inflammation." (PMID 22808256, 2012). "By day 6 post-infection, 90% of the wild type and TLR4−/− mice had succumbed to infection, while over 60% of the TLR2−/− mice survived and half of the survivors were symptom free throughout the study." (PMID 23061052, 2012). "During BHV-1 infection (Day 4), TLR4 expression levels in PMNs remained unchanged at 0.35 ± 0.44 (WMS) and 0.20 ± 0.70 (PA)." (PMID 22435642, 2012). "When we examined survival, we found that humanized TLR4/MD-2 mice succumbed to infection more rapidly compared with WT control mice, and the time to death in humanized TLR4/MD-2 mice was similar to TLR4/MD-2 KO mice." (PMID 23071439, 2012). "The mammalian immune system recognizes and responds to E. coli LPS via the TLR4 complex, resulting in the synthesis and secretion of pro-inflammatory cytokines that recruit immune cells to the site of infection." (PMID 23133372, 2012). "In contrast, both TLR4−/− and MyD88−/− mice exhibited early delays in systemic spread of infection during the first week, which is accompanied by a delay in clearance at later times." (PMID 22973560, 2012). "Conversely, upon initial infection, BM-induced an inflammatory suppressor, IL-10, from ATII cells and macrophages with delayed secretion of inflammatory cytokines via TLR4 at 20 h post-infection." (PMID 23293773, 2012). "The TRIF-dependent pathway is indispensable for the induction of type 1 IFNs through TLR3 and TLR4, but the role of type 1 IFNs in the resistance to infection with T. cruzi is controversial." (PMID 22496959, 2012). "In the presence of the TLR4 inhibitor, polymyxin B, infection of RANKL-primed RAW-D cells with P. gingivalis also induced osteoclastogenesis, indicating that TLR4 is not involved." (PMID 22723864, 2012). "Disease severity correlates to greater TLR4 protein expression on splenic lymphocytes in male mice 3 days after infection while resistance in females correlates to preferential TLR2 expression, especially in spleen lymphocytes." (PMID 23241283, 2012). "Another unexpected observation in this study was the delay in infection of the spleens and livers of TLR4−/− and MyD88−/− mice 1–2 weeks post-inoculation." (PMID 22973560, 2012). "We assessed the effect of triggering TLR2, TLR3, TLR4, and TLR7 with selected ligands on the susceptibility of the J774A.1 macrophage cell line to infection with murine coronavirus (mouse hepatitis virus, [MHV])." (PMID 22754655, 2012). "From week 2 and onward, TLR2−/− and TLR4−/− mice controlled infection and cleared the organisms from the livers indistinguishably from the C57BL/6 mice (panel W10)." (PMID 22973560, 2012). "Further studies from their laboratory have shown that male mice have increased levels of TLR4 expression on macrophages found in the heart following infection." (PMID 23241283, 2012). "Once established infection proceeds similarly, although the MyD88−/− and TLR4−/− mice exhibit a delay in clearance relative to the TLR2−/− and C57BL6 mice (panels W6–10)." (PMID 22973560, 2012).
infection (continued). "TLR4 signalling following infection increases cardiac interleukin (IL)-1β and IL-18 resulting in a more prominent T helper type 1 (Th1) immune response in males." (PMID 21338512, 2011). "We also demonstrate the significance of TLR4 in murine infection with C. difficile, with TLR4−/− and MyD88−/− mice displaying a more severe infection than wild type." (PMID 21738466, 2011). "Total number of PMN and NK cells after infection with Vi+ or Vi−S. Typhimurium in TLR4−/− and MyD88−/− mice." (PMID 21829346, 2011). "TLR4 has also been demonstrated to play a crucial role in protection from acute lethal infection by Leptospira interrogans serovar Icterohaemorrhagiae and in the control of leptospiral burden during sublethal chronic infection." (PMID 21909400, 2011). "In contrast, although the response to SGB1 Vi− infection in TLR4−/− and MyD88−/− was reduced compared to that in WT mice, there was still a significant response compared to naïve mice." (PMID 21829346, 2011). "Only CXCL10 expression was significantly attenuated in TLR4 mutant mice at day 3 post-infection, whereas the majority of mediators, including CCL2, CXCL1, and IL-1β were similar between TLR4 mutant and WT mice across all time points examined." (PMID 21496301, 2011). "As expected, TLR4 signal activation by CD4-TLR4 reduced the CD4-independent vector infection in 293T cells." (PMID 21541353, 2011). "Two SNP loci, 1 in TLR4 and 1 in TLR10, were associated with decreased odds of infection given increasing copies of the minor allele." (PMID 22164200, 2011). "In order to confirm that SLPs were recognised in the context of the whole bacterium and that TLR4 is necessary for their recognition, wildtype and TLR4−/− mice were infected as before with C. difficile and serum was collected 3 days post infection." (PMID 21738466, 2011). "The interplay between TLR2 and TLR4 expression during infection has been demonstrated in in vivo and in vitro models." (PMID 21789185, 2011). "Our group was able to demonstrate a downregulation of TLR2 and TLR4 after infection with the septicemic GBS strain ATCC® 13813 after 4 h, 8 h, and 24 h, respectively, compared to unstimulated cells." (PMID 21437210, 2011). "Nuclear p65 protein in WT mice was comparable among HC mice and stable at 6 h PI, while HC TLR2−/− and TLR4−/− mice had variable nuclear p65 levels pre-infection (intra-experiment variability) and between-strain similarity in nuclear p65 levels at 6 h PI." (PMID 21966468, 2011). "This has been seen during pulmonary H5N1 influenza A virus infection where ROS production generates oxidized phospholipids, which are TLR4 agonists playing a key role in lung injury during infection." (PMID 21949653, 2011). "WT, TLR2−/− and TLR4−/− mice were infected with CP as before and the numbers of Tregs in the lung were assessed by flow cytometry 5 days after infection." (PMID 21695198, 2011). "Strikingly, we also found that at the time of sensitization (5 days after infection), TLR4−/− mice actually had much greater numbers of Tregs than TLR2−/− or WT mice." (PMID 21695198, 2011). "We therefore compared MAP kinase signalling following L. mexicana promastigote infection in macrophages deficient in TLR-2 and TLR-4 or both." (PMID 21664694, 2011). "The TLR4 signal activation also attenuated the CD4-independent vector infection by enhancing cathepsin B expression." (PMID 21541353, 2011). "TLR4 signal activation by the CD4-TLR4 attenuated the CD4-independent HIV-1 vector infection by enhancing cathepsin B expression, suggesting that cathepsin B functions as an innate immune factor resisting the CD4-independent HIV-1." (PMID 21541353, 2011). "TLR4 (+) cells increased significantly (p < 0.01) in the infection control group (S) and in mice fed continuously with the probiotic strain (Lc-S-Lc) compared to the untreated control (C)." (PMID 21813005, 2011).
infection (continued). "We observed that baseline levels of Tregs in the lung were significantly reduced in TLR2−/− mice compared to WT and TLR4−/− mice, which was maintained at 5 days after infection, during the time when sensitization would begin." (PMID 21695198, 2011). "During short-term infection, aortic expression of both Tlr2 and Tlr4 was significantly up-regulated." (PMID 21625524, 2011). "For example, the recognition of Mycobacterium tuberculosis, a Gram-positive bacterium, by TLR4 is critical for elimination of the pathogen and containment of the infection to the lungs." (PMID 21738466, 2011). "The fact that TLR4 had little impact on the course of infection strongly suggests the involvement of alternative TLRs as well as the IL-1R and IL-18R, which also utilize MyD88 as an adaptor." (PMID 21496301, 2011). "We found that TLR2 was 6-fold up-regulated 24 h after infection solely in infected quarters and accordingly TLR4 2-fold." (PMID 20184744, 2010). "TLR4 was subsequently shown to control the response to infection of epithelial cells lining the urinary tract mucosa." (PMID 20505764, 2010). "TLR4 and TIRAP/Mal polymorphisms in 375 general surgical patients were associated with risk of infection, clinical course and outcome." (PMID 20525286, 2010). "Early in the infection, TLR4 stimulation by LPS results in a strong inflammatory response, neutrophil recruitment, and elaboration of antimicrobial peptides." (PMID 20657847, 2010). "Recently, the contribution of S100A8/A9 protein complex during infection has been appreciate again due to its pro-inflammatory properties and interaction with TLR4." (PMID 20976233, 2010). "Significantly lower production of NO was also found in splenocyte cultures from Tlr4−/− mice at day 10 post infection." (PMID 20442858, 2010). "It is well known that during acute infection LPS triggers intracellular signaling cascades via Toll-like receptor TLR4 that rapidly induce inflammatory cytokines that initiate a variety of overlapping immune responses." (PMID 20526368, 2010). "Ceramide activates a TLR4-dependent innate immune response, similar to infection-mediated activation, and we have proposed that ceramide acts as a signaling intermediate between the pathogen-specific receptors and TLR4." (PMID 20886096, 2010). "Increased CFU was also detected in TLR4−/− corneas infected with the Af-BP clinical isolate at 48h and 72h after infection, indicating that the role for TLR4 is consistent among Af strains." (PMID 20617171, 2010). "We analyzed the induction of IFN-γ and cytotoxic activity in vivo in TLR2-, TLR4-, TLR9- or MyD88-deficient mice during infection, and found intact responses compared to WT mice." (PMID 20442858, 2010). "Stimulation of these PRRs (TLR-2, TLR-4, and dectin-1) during infection with A. fumigatus subsequently leads to activation of transcription factors such as NF-κB, whose translocation into the nucleus stimulates the upregulation of pro-inflammatory cytokines." (PMID 20368800, 2010). "Stimulation of PRRs (TLR-2, TLR-4, and dectin-1) during infection with A. fumigatus leads to activation of transcription factors such as NF-κB, whose translocation into the nucleus stimulates upregulation of pro-inflammatory cytokines." (PMID 20368800, 2010). "In accord with those results, we found that after 2.5 h of infection, TLR4 and parasite co-localize into acidic compartments." (PMID 20442858, 2010). "Helicobacter spp.-positive (Hsp+) IL-10−/− mice also deficient in TLR4 (TLR4−/− x IL-10−/− [DKO]) exhibit earlier onset and increased severity of typhlocolitis, which is dependent upon infection with Helicobacter spp.." (PMID 20976045, 2010). "In our previous work, we showed a reduced expression of both TLR2 and TLR4 in monocytes from those trauma patients who developed any infection." (PMID 21184675, 2010).